TJP1 (tight junction protein 1)
Description:
TJP1, TJP2, and TJP3 are closely related scaffolding proteins that link tight junction (TJ) transmembrane proteins such as claudins, junctional adhesion molecules, and occludin to the actin cytoskeleton. Forms a multistranded TJP1/ZO1 condensate which elongates to form a tight junction belt, the belt is anchored at the apical cell membrane via interaction with PATJ (By similarity). The tight junction acts to limit movement of substances through the paracellular space and as a boundary between the compositionally distinct apical and basolateral plasma membrane domains of epithelial and endothelial cells. Necessary for lumenogenesis, and particularly efficient epithelial polarization and barrier formation (By similarity). Plays a role in the regulation of cell migration by targeting CDC42BPB to the leading edge of migrating cells. Plays an important role in podosome formation and associated function, thus regulating cell adhesion and matrix remodeling. With TJP2 and TJP3, participates in the junctional retention and stability of the transcription factor DBPA, but is not involved in its shuttling to the nucleus (By similarity). May play a role in mediating cell morphology changes during ameloblast differentiation via its role in tight junctions (By similarity).
Synonyms: ZO-1; MGC133289; DKFZp686M05161
Tractability: Small molecule: it has a binding pocket of medium quality. Antibody: UniProt places it where antibodies can reach, with high confidence; its Gene Ontology location is reachable by antibodies, with high confidence. PROTAC: ubiquitination databases record sites on it; its protein half-life has been measured.
Gene: Protein-coding gene on chromosome 15 (29,699,367 to 29,968,915, reverse strand). Ensembl gene ENSG00000104067.
Subcellular location: Cell membrane; Cell junction, tight junction; Cell junction; Cell junction, gap junction; Cell projection, podosome
Subcellular location (Human Protein Atlas): Cell Junctions
Pathways (Reactome):
Disease: Dengue Virus-Host Interactions; SARS-CoV-2 targets PDZ proteins in cell-cell junction
Gene expression (Transcription): RUNX1 regulates expression of components of tight junctions
Programmed Cell Death: Apoptotic cleavage of cell adhesion proteins
Signal Transduction: Signaling by Hippo
Vesicle-mediated transport: Regulation of gap junction activity
Gene Ontology:
Molecular function: cadherin binding; protein binding; cell adhesion molecule binding
Biological process: actin cytoskeleton organization; actomyosin structure organization; adherens junction maintenance; cell-cell junction organization; establishment of endothelial intestinal barrier; negative regulation of apoptotic process; positive regulation of blood-brain barrier permeability; positive regulation of cell migration; positive regulation of cell population proliferation; positive regulation of cell-cell adhesion mediated by cadherin; positive regulation of sprouting angiogenesis; protein localization to adherens junction; protein localization to bicellular tight junction; protein localization to cell-cell junction; regulation of bicellular tight junction assembly; regulation of cell junction assembly; regulation of cytoskeleton organization; ameloblast differentiation; cell-cell adhesion; cell-cell junction assembly; maintenance of blood-brain barrier; negative regulation of stress fiber assembly
Cellular component: anchoring junction; apical junction complex; apical part of cell; basolateral plasma membrane; bicellular tight junction; cell junction; cytoplasm; plasma membrane; protein-containing complex; tight junction; adherens junction; cytosol; gap junction; nucleoplasm; podosome
Genetic constraint (gnomAD): Loss-of-function variants: 38 observed, 180.86 expected, observed/expected ratio (o/e) 0.21, 90% interval 0.16 to 0.28. The upper end of that interval is the gene's LOEUF score, 0.28, which puts it in group 1 of 6, group 1 being the genes least tolerant of losing a copy. Missense variants: 1,911 observed, 2,196 expected, observed/expected ratio (o/e) 0.87, 90% interval 0.84 to 0.9. Synonymous variants: 785 observed, 791.66 expected, observed/expected ratio (o/e) 0.99, 90% interval 0.93 to 1.05.
Gene-disease validity (ClinGen):
ClinGen rates the evidence that TJP1 causes each of these diseases.
arrhythmogenic right ventricular cardiomyopathy (autosomal dominant): Limited.
Homologues: Orthologues: chimpanzee TJP1 (99% identical), macaque TJP1 (99% identical), guinea pig TJP1 (92% identical), rabbit TJP1 (92% identical), pig TJP1 (89% identical), mouse Tjp1 (88% identical), rat Tjp1 (87% identical), tropical clawed frog tjp1 (74% identical), zebrafish tjp1a (65% identical), zebrafish tjp1b (63% identical), Drosophila melanogaster pyd (31% identical), Caenorhabditis elegans zoo-1 (21% identical). Paralogues in human: TJP2 (32% identical), TJP3 (23% identical), DLG5 (13% identical).
Diseases named in the same sentence as TJP1 in open-access papers:
TJP1 is named in the same sentence as 387 diseases in open-access papers, as found by Europe PMC text mining. Sharing a sentence is not in itself a finding about the gene and the disease. The quoted sentences say what the papers report.
colitis (367 papers, 2007 to 2026). Inflammation of the colon. "Moreover, colitis has been associated with decreased transcription of ZO-1 (Tjp1) and claudin-5 (Cldn5) in the brain." (PMID 34983592, 2022). "However, as previously shown, OxA treatment after colitis induction increase the expression of tight-junction Tjp1 expression when compared to that with colitis induction without treatment." (PMID 37298505, 2023). "The decreased TJP1 expression level observed in inflamed IBD and UC mucosa, compared to non-inflamed mucosa, is consistent with a loss of ZO-1 protein (encoded by TJP1) in dextran sulfate sodium induced colitis in mice." (PMID 28545409, 2017). "The involvement of MAPKs in the favorable effects of nicotine on DSS-induced colitis was also highlighted by the inferred downregulation of Map3k5 that would, according to the IBD model, decrease translocation of Ocln and Tjp1 from tight junctions to the cell membrane." (PMID 37047398, 2023). "In the preventive trial with DSS-colitis, dexamethasone-induced an increase in Hif1a and Il6, and a decrease in Tjp1 expression compared to controls, while Tgfb1 and Vegfa expression was increased in the MTADV group, as well as Nos2 and Tjp1 in comparison to dexamethasone." (PMID 37047397, 2023). "These latter correlations were maintained mainly in females, who additionally displayed a strong positive correlation with Vegfa and Tjp1, and a negative correlation with Nos2 in therapeutic DSS-colitis and positive ones with Nos2 and Tnfa in preventive TNBS-colitis." (PMID 37047397, 2023).
breast cancer (100 papers, 2005 to 2025). A primary or metastatic malignant neoplasm involving the breast. "In breast cancer, Tjp1 is reduced in poorly differentiated tumors and is associated with an increase in tumor grade and TNM (tumor-nodal) status." (PMID 38255907, 2024). "Decreased TJP-1 expression is correlated with increased invasiveness in breast cancer, colorectal cancer, and cancers of the human digestive tract." (PMID 38255907, 2024). "Downregulation of TJP1 expression has been observed in gastrointestinal adenocarcinoma, breast cancer, and colorectal carcinoma." (PMID 35087173, 2022). "Exosomes containing miR-105 can be released by metastatic breast cancer cells to destroy the vascular endothelium barrier targeting the tight junction protein 1 (TJP1) in endothelial cells (recipient cells) and promoting cancer metastasis." (PMID 34440837, 2021). "Also, the inactivation of CXCL12 stabilized endothelial tight junction expression like TJP-1 and occludin in breast cancer metastasis." (PMID 32210974, 2020). "It has been shown that an FOXN3–NEAT1–SIN3A complex promotes the invasion of breast cancer cells and EMT in vitro and the proliferation and metastasis of breast cancer in vivo by inhibiting the transcription of downstream target genes GATA3 and TJP1." (PMID 31214490, 2019).
Stroke (72 papers, 2013 to 2026). Sudden impairment of blood flow to a part of the brain due to occlusion or rupture of an artery to the brain. "In stroke, vascular endothelial cell (EC) dysfunction at the compromised BBB involves paracellular leakage, as evidenced by the degradation of tight junction (TJ) proteins including claudin-5 (CLDN5), occludin (OCLN), and zonula occludens-1 (ZO-1/TJP1)." (PMID 40866935, 2025).
diabetes (50 papers, 2012 to 2026). "The reduction in and redistribution of TJP1 in glomerular podocytes has also been seen in animal models of diabetes." (PMID 38891801, 2024).
lung cancer (40 papers, 2009 to 2025). A malignant neoplasm involving the lung. "The TJP1 gene encodes the ZO‐1 protein, which has been implicated in the dysfunction of TJs in various diseases, such as aortic dissection and non‐small cell lung cancer (NSCLC)." (PMID 39900554, 2025). "Three genes, TFAP2A, TJP1 and TMEM63B, have been shown to be associated with the B lymphocytes in lymph node metastasis of lung cancer." (PMID 34575089, 2021). "Zonula occludens-1 (ZO-1) which is a tight junction protein-1 induces the NF-κB dependent synthesis of IL-8 in breast and lung cancer cell lines." (PMID 34220337, 2021). "Recently, it was shown that TGF-ß increases the expression of TJP1 and enhances cell motility of lung cancer cells." (PMID 28376875, 2017). "For instance, RBM47 regulated TJP1 alternative splicing to promote lung cancer EMT transition." (PMID 37660095, 2023). "Further verifying our findings about the pivotal role of both SDF-1 receptors on stabilizing cellular integrity, inhibition of CXCR4 increased TJP-1, occludin, and claudin 5 in the blood/brain barrier in terms of an ischemic stroke and brain-specific metastasis in lung cancer." (PMID 32210974, 2020). "Profiling the epithelial‐mesenchymal transition‐related molecular markers demonstrated decreased CDH1, TJP1, and OCLN and increased ZEB1, FN1, and EZH2 in response to CDKN2A silencing in lung cancer cells." (PMID 33155773, 2020). "What’s more, they found four target genes of miR-155 including HBP1, TJP1, SMAD5 and PRKAR1A involved in the oxidative stress process of lung cancer." (PMID 31727002, 2019). "Furthermore, it has been demonstrated that exosomal miR-23a, overexpressed in hypoxic lung cancer, enhanced angiogenesis and vascular permeability through its targets prolyl hydroxylase (PHD) and tight junction protein-1 (also known as zonula occludens-1, ZO-1)." (PMID 31242686, 2019).
Obesity (38 papers, 2018 to 2025). Accumulation of substantial excess body fat. "Tjp1 encodes ZO-1, which is a scaffold protein which cross-links and anchors tight junction strand proteins regulating intestinal permeability and has been shown to be altered in obesity." (PMID 38255939, 2024). "HFD-induced mild obesity increased the transcription of Occludin1 and TJP1, key markers of barrier integrity." (PMID 40509380, 2025). "Cell junction proteins showed enriched expression in fenestrated ECs, and Jam3, Pdch12, Afdn and Tjp1 were upregulated in obesity in fenestrated ECs." (PMID 36400935, 2022). "Importantly, the ACM obtained from patients with obesity downregulated the expression levels of TJP1 and MUC2, suggesting a crosstalk between adipocytes and intestinal cells in which the pro-inflammatory profile of adipocytes may impair the integrity of intestinal barrier." (PMID 38315242, 2024).
colorectal cancer (34 papers, 2010 to 2025). A primary or metastatic malignant neoplasm that affects the colon or rectum. "RBM47 mRNA was decreased in human colorectal cancer versus paired normal tissue, along with alternative splicing of tight junction protein 1 mRNA." (PMID 37014710, 2023). "This study demonstrates a novel AS pattern of tight junction protein 1 (ZO1) regulated by the RNA polymerase II elongation rate in colorectal cancer (CRC)." (PMID 35218185, 2022). "Moreover, the depletion of RBM47 led to the downregulation of epithelial-associated genes including OCLN, CDH1, TJP1, and CLDN1 with a concomitant enhancement in cell migration, mesenchymal markers, invasion and metastasis in colorectal cancer, which was consistent with our report." (PMID 35831298, 2022).
inflammatory bowel disease (33 papers, 2008 to 2026). A spectrum of small and large bowel inflammatory diseases of unknown etiology. "In this line, zonulin-1, the protein encoded by the TJP1 gene, is essential for intestinal mucosal repair and is downregulated both at a transcript and protein level in intestinal samples from patients with inflammatory bowel disease." (PMID 39305371, 2025).
endotoxemia (32 papers, 2014 to 2025). "Oral administration of P. gingivalis significantly increased endotoxemia and reduced mRNA expression of ZO-1, occludin, and Tjp1 tight junction proteins in the small intestine." (PMID 33652903, 2021). "Moreover, the oral administration of P. gingivalis in mice was also found to significantly exacerbate endotoxemia while reducing the transcription of genes such as ZO-1, occludin and Tjp1 tight junction proteins in the small intestine." (PMID 34064692, 2021). "Moreover, downreguation in gene expression of the intestinal tight-junction proteins Tjp1 and Ocln indicated disruption of the intestinal barrier, which was mainly attributed to endotoxemia." (PMID 31450675, 2019).
Hyperglycemia (32 papers, 2013 to 2026). An increased concentration of glucose in the blood. "We also investigated the effects of hyperglycemia on gene expression of tight junction proteins ZO-1 (TJP1), Claudin 1 (CLDN1), and Occludin (OCLN)." (PMID 38110453, 2023).
ulcerative colitis (30 papers, 2013 to 2026). An inflammatory bowel disease involving the mucosal surface of the large intestine and rectum. "Allelic associations between TJ-related genes (F11R, MAGI1, MAGI2, MAGI3, PARD3, PTEN, and TJP1) and IBD, Crohn’s disease (CD), or ulcerative colitis (UC) were investigated." (PMID 28545409, 2017).
glioma (29 papers, 2008 to 2025). A benign or malignant brain and spinal cord tumor that arises from glial cells (astrocytes, oligodendrocytes, ependymal cells). "qRT-PCR showed that CDH1 and TJP1/ZO-1 levels were lower than controls, indicating a reduced epithelial phenotype in higher-grade gliomas." (PMID 40679044, 2025). "NOTCH1, SOX2, TJP1/ZO1, ZEB1, and ZEB2 have higher expression in lower-grade glioma vs GBM." (PMID 40679044, 2025).
colon carcinoma (24 papers, 2012 to 2026). "Correspondingly, we found that colonic cancer cells responded to IL-4 and IL-13 stimulation with upregulation of CLDN2, significantly so in case of IL-4, while ACTA2 and TJP1 tended to be rather downregulated, significantly so in case of Caco-2 stimulation with IL-4." (PMID 32512917, 2020).
melanoma (20 papers, 2008 to 2025). A malignant, usually aggressive tumor composed of atypical, neoplastic melanocytes. "We examined the effects of Tjp1 and Tjp2 KO expression on tumor growth and metastasis by subcutaneously and intravenously injecting separate groups of mice (10 per test group) with MOCK, Tjp1 and Tjp2 KO, or Tjp1 and Tjp2 re-expressed B16-F10 melanoma cells." (PMID 38255907, 2024). "In this study, we first knocked out Tjp1 and Tjp2 in B16-F10 mouse melanoma cells using the CRISPR–Cas9 system and analyzed the tumorigenic characteristics, such as invasion and migration, in vitro." (PMID 38255907, 2024). "In this study, we successfully generated Tjp1 and Tjp2 KO melanoma cells for the first time using the CRISPR/Cas9 system and demonstrated that TJ proteins are not only important for barrier function but also have a significant effect on cancer progression." (PMID 38255907, 2024). "We further investigated whether Tjp1 and Tjp2 KO stimulated the metastatic potential of B16-F10 melanoma cells." (PMID 38255907, 2024). "In vivo, in the metastatic model of melanoma, RNase A suppressed metastases in the lungs and changed the expression of EMT markers in the tissue adjacent to metastatic foci; this increased Cdh1 and decreased Tjp1, Fn and Vim, disrupting the favorable tumor microenvironment." (PMID 35745743, 2022).
brain edema (17 papers, 2012 to 2025). Increased intracellular or extracellular fluid in brain tissue. "Interestingly, cerebral oedema may be a consequence of reduced expression of Tjp-1 (RQ = 0.84 ± 0.03, p = 0.01)." (PMID 22920500, 2012).
pancreatic cancer (17 papers, 2008 to 2025). "A recent study revealed that the expression of Tjp1 is decreased in human lung diseases associated with inflammation and in pancreatic cancer cell lines, and the knockdown (KD) of Tjp1 and claudin-1 contributes to tumor migration and invasion in xenograft tumors." (PMID 38255907, 2024).
endothelial dysfunction (15 papers, 2014 to 2025). In vascular diseases, endothelial dysfunction is a systemic pathological state of the endothelium (the inner lining of blood vessels) and can be broadly defined as an imbalance between vasodilating and vasoconstricting substances produced by (or acting on) the endothelium. "In addition, ROS dependent activation of Ras and ERK1/2 Kinase was observed to be mediating the TJP-1 disassembly, and endothelial dysfunction in response to cocaine and Tat exposure." (PMID 24409324, 2014).
hepatocellular carcinoma (15 papers, 2015 to 2025). A malignant tumor that arises from hepatocytes. "LSF fosters a highly aggressive and metastatic phenotype in different hepatocellular carcinoma (HCC) cells and can target fibronectin 1 (FN1) and tight junction protein 1 (TJP1) to mediate HCC metastasis." (PMID 27626695, 2016).
Salmonella Infections (15 papers, 2014 to 2025). Infections with bacteria of the genus SALMONELLA. "Besides, the salmonella infection significantly decreased (P < 0.05) the expression of intestinal barrier-related proteins, such as ZO-1 (TJP1) and OCLN-1 in the duodenum, jejunum, and ileum." (PMID 35371085, 2022). "For the G2 group, the main pathways were: Salmonella infection (NFKB1, TJP1, DYNC2H1), transcriptional misregulation in cancer (MET, MLLT1, NFKB1), and adherens junction (MET, TJP1)." (PMID 36012418, 2022).
Chronic colitis (14 papers, 2015 to 2026). A chronic inflammatory disease of the large intestine (colon, cecum and rectum). "Interestingly, Foxp3YFP‐cremiR‐10afl/fl mice showed an increased intestinal barrier integrity compared with Foxp3YFP‐cremiR‐10afl/+ mice in the DSS‐induced chronic colitis model, as demonstrated by a higher level of IEC tight junction protein 1 (Tjp1) in Foxp3YFP‐cremiR‐10afl/fl mice." (PMID 41178490, 2026).
lung adenocarcinoma (12 papers, 2015 to 2023). A carcinoma that arises from the lung and is characterized by the presence of malignant glandular epithelial cells. "TFAP2A and TJP1 have both been identified in the lymph node of lung adenocarcinoma as potential biomarkers." (PMID 34575089, 2021). "For example, RBM47, an important RNA-binding protein, was proved to promote EMT by regulating AS of tight junction protein 1 (TJP1) and suppress tumor growth via inhibiting nuclear factor erythroid 2-related factor 2 (NRF2) activity in lung adenocarcinoma." (PMID 34212178, 2021).